CXCR4 (C-X-C motif chemokine receptor 4)
Diseases named in the same sentence as CXCR4 in open-access papers (continued):
Sharing a sentence is not in itself a finding about the gene and the disease.
tumor (continued). "We found that CXCR4 and c-Kit also co-expressed with Oct4 indicative of PGC-like cells, but they were almost undetectable in Oct4–/low somatic tumor cells under in vitro cell culture of various cell lines." (PMID 32218989, 2020). "This review summarizes the downstream cell signaling transduction of CXCL12/CXCR4/CXCR7 axis (abbreviation: CXCL12 axis) and the role of CXCL12 axis in tumor progression, growth, survival, angiogenesis, metastasis, and chemoresistance." (PMID 33363463, 2020). "For example, exosomes released from bone marrow mesenchymal stem cells can be internalized in tumor cells and elicit angiogenesis through transferring VEGF, CXCR4, α-SMA, and MDM2 mRNA transcripts." (PMID 32499786, 2020). "The present study evaluated the diagnostic significance of selected receptors for chemokines (CXCR4 and CXCR2) in comparison to the well-established tumor marker–CEA." (PMID 32867211, 2020). "The CXCL12/CXCR4/CXCR7 axis plays key roles in many physiological and pathological processes, including embryogenesis, wound healing, angiogenesis, tumor development, as well as recruiting suppressive immune cells." (PMID 32381016, 2020). "We found a statistically significant correlation between CXCR4 and TMB, CYT, tumor purity, tumor immune infiltration, drug sensitivity, and other clinical parameters playing an important role in GC insurgence and development." (PMID 32306562, 2020). "There was a statistically significant correlation between CXCR4 levels and TMB, CYT, tumor purity, tumor immune infiltration, and drug sensitivity." (PMID 33182840, 2020). "For example, SDF-1/C-X-C Motif Chemokine Receptor 4 (CXCR4), a chemokine/chemokine receptor axis involved in stem cell trafficking and cancer metastasis, plays a major role in MSC tumor infiltration." (PMID 32133358, 2020). "For example, IL-15 stimulates migration of CD56bright NK cells to the tumor site by increasing the expression of CCR5, while inhibiting trafficking of CD56dim counterparts by decreasing CXCR4 and CX3CR1 expression." (PMID 33260925, 2020). "The in vitro and in vivo evaluation of SSTR2/CXCR4 mAbs-EV-Ver-A/DM1 showed high NET-specific targeting and high efficacy to inhibit tumor growth in xenograft mouse model." (PMID 33187322, 2020). "Dual expression of CXCR4 and CD133 has been used to identify an OC population with stem cell-like properties that regulate tumor development and chemoresistance." (PMID 32257947, 2020). "CAF-derived CXCL12 directly promoted tumor cell EMT and invasion by acting through CXCR4 on tumor cells and downstream activation of the P38 pathway." (PMID 33050580, 2020). "Their low levels in orthotopic tumors indicated that transplanted CXCR4+MET+CD44+ cells differentiated and lost marker expression during tumor formation." (PMID 32066735, 2020). "Increased tumor cell proliferation and growth were also found to be exerted by CXCL12 and its two receptors, CXCR4 and CXCR7/ACKR3, primarily in the context of hormonal stimulation." (PMID 32582148, 2020). "In chemotherapy-treated mouse tumors, TAMs which expressed CXCR4 were predominant cells in the TME and CXCR4 inhibitor monotherapy was found to block M2-like TAMs, resulting in the inhibition of tumor progression." (PMID 35582437, 2020). "Kisspeptin-10 (KP-10) can inhibit tumor cell invasion and EMT induced by SDF-1 through down-regulating CXCR-4 expression." (PMID 33262947, 2020). "A previous study determined that CXCR4 was highly expressed in DLBCL cell lines, and in a patient with DLBCL, [68Ga]pentixafor PET/CT resulted in excellent tumor uptake." (PMID 32757068, 2020).
tumor (continued). "Meanwhile, expression of the three chemokines were correlated to histological type, tumor differentiation, LVI and survival; expression of CXCR4 and CCR7 were also correlated to recurrence; and CCR7 expression differed notably between sexes." (PMID 32896997, 2020). "CXCL12 and its receptors, CXCR4 and CXCR7, have been identified as the key factors in tumor development and metastasis Ovarian epithelial tumor cells express high levels of CXCL12." (PMID 33363463, 2020). "In tumor cells, CXCL12 induces transendothelial migration, and thus the metastatic spread of CXCR4+CXCR7+ cells." (PMID 32098047, 2020). "CD73 expression was significantly increased within the subset of CD133+CXCR4+ MICs (median value= 80%; min 14%, max 100%) compared to CD133+ CSCs (median= 44%; min 2%, max 95%) and bulk tumor (median= 46%; min 2.5%, max 65%)." (PMID 33123122, 2020). "CXCL12 binds to the receptors C-X-C Motif Chemokine Receptor 4 (CXCR4) and C-X-C Motif Chemokine Receptor 4 (CXCR7) and thus regulates tumor growth and tumor metastasis." (PMID 32498358, 2020). "Nevertheless, our study provides further evidence for the theranostic potential of CXCR4 and CXCR7 in ACC, with special emphasis on potentially improving tumor response to systemic therapies." (PMID 33281749, 2020). "We and others, previously demonstrated that GSCs migrate from the tumor mass toward the SVZ, through the CXCL12/CXCR4 axis or through a pleiotrophin-driven axis." (PMID 33575218, 2020). "We synthesized 6 iodinated and brominated cyclam derivatives with high affinity (low nM range) for CXCR4, since structure-based estimates of lipophilicity suggested rapid transfer across the BBB and tumor cell membranes." (PMID 32239371, 2020). "Chemokine stromal cell-derived factor 1 (SDF-1) binds to chemokine (C-X-C motif) receptor 4 (CXCR4), which plays a vital role in tumor cell metastasis." (PMID 32836215, 2020). "However, considering that CXCR4 may be up-regulated by epigenetic alterations or hypoxia-driven signaling which allow tumor cells to adapt and win the selection leading to tumor cell dissemination and metastasis in a new host environment, inhibition of IGF2BP3 may be more relevant." (PMID 32719743, 2020). "In a lymphoma murine model, adoptively transferred CD8 T cells, overexpressing CXCR4, were preferentially recruited by CXCL12 expressing cells in the bone marrow, to promote tumor control." (PMID 33013822, 2020). "While CXCR4 and CXCL12 were homogeneously expressed within tumor cells, ACKR3 was mainly identified in tumor endothelial cells but CXCL11 in pericytes." (PMID 32456359, 2020). "As shown by the increased IVIS luminescence detection, overexpression of ERα in A549 cells can increase the tumor growth, which can be reduced by CCR2 antagonist, CXCR4 antagonist AMD3100, or anti‐estrogen fulvestrant in vivo." (PMID 32356397, 2020). "Consistent with previous studies, we found that CXCR4 was significantly up-regulated in ESCC tissues, and correlated with tumor invasion and survival." (PMID 32232002, 2020). "Targeting of either CXCR-4 (CXCL-12 receptor) in breast human cancer cells or CXCL-12 in ZF significantly inhibited extravasation and metastatic tumor growth at the CHT area." (PMID 32225005, 2020). "The activation of CXCR4 by CXCL12 mediates tumor cell survival and proliferation and enhances primary tumor progression, angiogenesis and metastasis." (PMID 33392074, 2020). "For example, the CXCL12/CXCR4 signaling boosts the activity of PI3K and ERK promoting tumor growth and drug resistance in TNBC cells." (PMID 33096815, 2020). "More recently, the chemokine CXCL12 and its cognate receptors (CXCR4 and CXCR7) have been shown to play central roles in cancer proliferation, angiogenesis, invasion, tumor microenvironment, as well as drug resistance induced by chemotherapy." (PMID 33363463, 2020).
tumor (continued). "Moreover, crosstalk regulation between the mTOR pathway and the CXCL12/CXCR4 axis suggests that mTORC1 silencing is sufficient to decrease CXCR4-mediated cancer cell migration, and inhibition of mTORC1 by rapamycin decreases primary tumor growth and CXCR4-mediated lymph node metastasis." (PMID 32498358, 2020). "In a previous work, we reported the NFkB-induced expression of CXCR7 concomitant to the perturbation of the CXCR4/CXCL12 and VCAM-1/VLA-4 integrin axes, consistent with experimental evidence of its involvement in immune cell recruitment and tumor metastasis." (PMID 33062419, 2020). "Following co-culturing of the tumor cells with CAFs, a process that has led to increased production of CXCL12, CXCR4 inhibition has reduced the formation of spheroids that were enriched with CD44+/CD24− cells." (PMID 32582148, 2020). "Similar to CXCR4, CXCR7 plays a role in angiogenesis and tumour growth with its expression correlates with metastasis." (PMID 32512633, 2020). "For example, eliminating or silencing the expression CXCR4 and HDAC will have a profound impact in EAC accompanied by long-lasting tumor suppression effect theoretically." (PMID 32998713, 2020). "To identify a suitable tumour-specific promoter for the generation of an advantageous replication conditional HSV-1, we explored the CXCR4, Survivin/BIRC5 and TERT genes, known for their high level of expression in tumours." (PMID 32152425, 2020). "We aimed to explore the tumor expression of HGF, c-MET, CXCL12, and CXCR4 and their correlation with patient overall survival (OS)." (PMID 32188473, 2020). "Confocal imaging verified predicted interactions in the tumor stroma, illustrating CSFR1+, CXCR4+, and C3aR+ myeloid cells in close contact with CD34high fibroblasts." (PMID 32433953, 2020). "Given the role of ROS in mediating the communication between tumor cell and tumor microenvironment (TME), we sought to explore the effects of the antioxidant agent NAC on both CXCR4 activation and EMT trans-differentiation process of K562shFtH." (PMID 32432042, 2020). "The administration of a CXCR4 antagonist (AMD3100) induced rapid T-cell accumulation among the cancer cells and, in combination with anti-PD-L1, synergistically decreased tumor growth." (PMID 32575838, 2020). "Combination therapy consisting of XRT and CXCR4 inhibition with AMD3100 decreased angiogenesis and increased vasculogenesis and abrogated tumor recurrence within the 100-day follow-up period." (PMID 32239371, 2020). "We found further that Calebin A significantly suppressed TNF-β-induced phosphorylation and nuclear translocation of p65-NF-κB, similar to BMS-345541 (specific IKK inhibitor) and NF-κB-induced tumor-promoting biomarkers (NF-κB, β1-Integrin, MMP-9, CXCR4, Ki67)." (PMID 32244288, 2020). "Here, we have evaluated matrine for its activity on C-X-C chemokine receptor type 4 (CXCR4) and matrix metalloproteinases (MMP-9/2) expression, and its potential to affect tumor metastasis and invasion." (PMID 32630806, 2020). "CXCR4 activation by C-X-C motif chemokine 12 (CXCL12) promotes tumour growth in para and autocrine fashion and fosters tumour cell migration as well as metastatic spread." (PMID 31959787, 2020). "As MMP‐2 is preferentially accumulated in tumors but not normal tissues, this feature avoids potential side effects of melittin to normal tissues and provides further tumor‐targeting specificity on top of the interaction between AMD3100 and CXCR4." (PMID 32154067, 2020). "Expression levels of CXCR4, CXCR5 and CCR7 were significantly higher in tumor tissues, and expression of CXCR5 and CCR7 were independent prognostic factors for survival." (PMID 32896997, 2020). "It has been demonstrated that CXCR4 can bind to SDF-1, which activates ERK/AKT signaling or PI-3K signaling to regulate tumor cell proliferation." (PMID 32368286, 2020).
tumor (continued). "Changes in the RNA levels of chemokine receptors were consistent with this maturation defect, with bone-marrow derived neutrophils from tumor-bearing castrated mice characterized by decreased CXCR2 and increased CXCR4 and VLA4." (PMID 32235862, 2020). "Functional analyses identified miR-9 as a potential tumor suppressor in the development and progression of GBM through the targeting of the key metastasis promoter, CXCR4." (PMID 32635336, 2020). "Like SDF-1, tumor-secreted MIF binds, among other receptors, to CXCR4 (Gi-protein coupled receptor) and activates MAP kinase signaling pathway, eventually inducing MSC migration through upregulating cell motility genes." (PMID 32133358, 2020). "Marked co-localization of CXCR4 and CXCL12 in tumor cells was also shown in immunohistochemical examination of tumor samples, they were manifested predominantly in pseudopalisading in the areas of perinecrosis and microcystic degeneration." (PMID 32456359, 2020). "Chemokine receptors such as CXCR3, CXCR4 and CXCR7 play vital roles in the process of tumour progression and metastasis." (PMID 32512633, 2020). "Although CXCR4 is thought to be the canonical receptor, some recent studies have suggested a role for CXCR7 in tumor angiogenesis." (PMID 33106502, 2020). "Chemokine receptor-4 (CXCR-4) and its interaction with stromal cell-derived factor SDF-1 secreted on the surface of tumor cells is the most important set involved in MSCs tumor tropism." (PMID 32046010, 2020). "Chemokine axes such as CCL19, CCL21/CCR7, CCL20/CCR6, CXCL12/CXCR4, and CXCL13/CXCR5 correlate with B cell infiltration to tumor sites." (PMID 31991604, 2020). "In the present paper we demonstrated that serum CXCR4 and CXCR2 were significantly elevated in PC patients compared to healthy controls, similarly to the classical tumor marker and CRP." (PMID 32867211, 2020). "Analyses of the PBI-05204–treated U87 cells revealed significant 73% declines in expression of Sox2 and a moderate reduction of other tumor stem cell markers CD44 and CXCR4." (PMID 33013390, 2020). "Current prognostic markers include chemokines receptors CXCR3, CXCR4 and CXCR7, which are known to be involved in multiple tumour progression and metastasis." (PMID 32512633, 2020). "Diverse animal studies provided evidence that CXCR4 inhibitors allow mobilization of hematopoietic stem cells, suppression of CXCR4-tropic HIV-1 replication and reduction in tumor growth and/or metastasis." (PMID 32994431, 2020). "CXCL12/CXCR4 is the key signaling used to attract and cross-connect multiple cells within the TME aiming for tumor progression and metastasis." (PMID 32260318, 2020). "In adults, the SDF-1/CXCR4 axis plays a role in GBM development, tumor cell proliferation, and invasiveness via activation of matrix metalloproteinases (MMPs)." (PMID 32599834, 2020). "CXCR4 protein expression differences were also notable between microsatellite stable (MSS) and microsatellite instable (MSI) tumor cell lines." (PMID 32110952, 2020). "Mounting evidences supported that the CXCL12/ CXCR4 / CXCR7 axis was related to multiple types of solid tumors and tumor cells." (PMID 33129326, 2020). "The good news is that inhibitors of HIV protease or reverse transcriptase and CXCR4 antagonists, which have been used for many years to counter HIV infection, effectively inhibit MMP-9 expression and tumor cell dissemination." (PMID 32630531, 2020). "A CXCR4 inhibitor with PD-1 blockade increased tumor cell apoptosis and CD8 T cell clonal expansion and effector function in a human PDA tumor slice model." (PMID 33584701, 2020). "Neutrophils and myeloid derived suppressor cells (MDSCs) are recruited to the tumor through ligands for CCR2, CCR3, CXCR1, CXCR2, and CXCR4." (PMID 30873179, 2019). "Further experiments are warranted to elucidate the conflicting role of CD164 in SDF-1/CXCR4-dependent signaling in GBM, its impact on autophagy and apoptosis, and the ensuing effects on tumor growth and survival." (PMID 31007847, 2019).
tumor (continued). "By this metric, and on the basis of their high yielding radiosynthesis, high tumor uptake, and good contrast to background, [18F]RPS-547, and especially [18F]RPS-534, are promising 18F-labeled candidates for imaging CXCR4 expression." (PMID 31022852, 2019). "In conclusion, a positive feedback is established between tumour cells, TEMs, and TAMs: tumour cells recruit TEMs by expressing CXCL12, receptor to CXCR4, which is located on the TEM surface, and TAMs through CSF-1 and TGFβ." (PMID 31554160, 2019). "Tumours were harvested from the liver of control ADC- and ADC 713- treated mice at respective humane end-points to test CXCR4 expression on tumour cells." (PMID 30792442, 2019). "1, MUC-1), etc., CTSC surface markers include CD26, CD44, CD133 and CXC chemokine receptor 4 (CXCR4), etc., circulating EMT positive tumor cell surface markers are vimentin, fibronectin, calcium adhesion protein-N and calcium adhesion protein-O and so on." (PMID 31767014, 2019). "Western blots were used to verify the activation of Notch1/CXCR4/AKT pathway in self-renewal, invasion and tumor growth of GICs." (PMID 31382985, 2019). "Several chemokines (CCL2, CCL5, CXCL1, CXCL10 and CXCL12) produced by tumour and stromal cells activate their specific mast cell receptors (CCR2, CCR3, CXCR2, CXCR3 and CXCR4), which are important for TAMC localization in TME." (PMID 31035644, 2019). "Other molecules tested in TRUCKs are knock-out genes (PD-1 or DGK) and knock-in genes (TRAC or CXCR4), their aim to improve CAR expression and anti-tumor activity." (PMID 31619289, 2019). "Inflammatory cytokines derived from tumor conditioned monocytes/macrophages (Mo/Mφ), especially TNF-α, upregulate CXCR4 expression on ECs." (PMID 30800123, 2019). "CXCR4 is activated by SDF‐1 to increase vascular permeability, producing a variety of tumor cell lines that adhere to extracellular matrix substrates and vascular endothelial cells." (PMID 31665829, 2019). "It is noteworthy that activation of the MAPK/ERK and PI3K/Akt pathways is an important step required for EMT process induced by various tumor-related factors including TGF-β, TACC3, EGF, BMP7, ZNF143, and CXCR4 26-31." (PMID 31417642, 2019). "Interactions between CXCR4 and CXCL12 stimulate tumor cell migration and invasion of basement membrane preparation by increasing the formation of cell adhesion molecules like matrix metalloproteinases." (PMID 31248118, 2019). "ADC activity in CXCR4Low tumours was also observed in vivo (ex: OPM2 xenografts) and in these models CXCR4 expression in vivo remains as low as in vitro." (PMID 30792442, 2019). "The main chemokines involved in oral carcinogenesis, tumor invasion and metastasis are CCR4, CCR5, CCR7 and CXCR4, and our aim was to evaluate the prognostic value of the immunoexpression of these chemokines in SCC of tongue and floor of the mouth." (PMID 31011147, 2019). "CXCR4 is involved in tumor growth and metastasis in TNBC, implying that there is therapeutic promise for CXCR4-targeted agents." (PMID 32047724, 2019). "The C-X-C motif chemokine receptor 4 (CXCR4) is attractive for targeted therapy of haematological cancers, given its expression in multiple tumour types and role in cancer “homing” to bone marrow." (PMID 30792442, 2019). "These interactions showed increased expression of CXCR4 on monocytic MDSCs, with PGE2 inducing CXCL12 in the tumor microenvironment, as well as CXCR4 on MDSC precursor cells." (PMID 31354741, 2019). "5hmC and CXCR4 immunohistochemical staining was done on human PDAC TMAs and grading of intensity of stain in the tumor stromal CAFs was estimated." (PMID 31663852, 2019). "Increasing evidences demonstrated that CXCL12/CXCR4 promoted EMT and tumor invasion in CRC, miR-133a-3p was markedly downregulated in a variety of cancers and associated with tumorigenesis and metastasis." (PMID 30678736, 2019).